DNMT3B (DNA methyltransferase 3 beta)
Diseases named in the same sentence as DNMT3B in open-access papers (continued):
Sharing a sentence is not in itself a finding about the gene and the disease.
male infertility (2 papers, 2017 to 2019). The inability of the male to effect fertilization of an ovum after a specified period of unprotected intercourse. "The DNMT3B variant homozygote had a significantly decreased risk of male infertility in the Subgroup IV (adjusted OR, 0.25, 95% CI = 0.06–0.94, P = 0.040) compared with other genotypes." (PMID 28894282, 2017). "When the DNMT3B CC genotype was used as the reference group, the carrier of TT genotype in Subgroup IV had a significantly decreased risk of male infertility (adjusted OR, 0.26, 95% CI = 0.07–0.98, P = 0.046)." (PMID 28894282, 2017). "Variants of DNMT1 and DNMT3B are risk factors for idiopathic male infertility." (PMID 28894282, 2017). "The purpose of this study was to investigate the association between male infertility and single-nucleotide polymorphisms (SNPs) of DNA methyltransferases (DNMT) genes (DNMT3B: rs2424909, DNMT1: rs4804490, DNMT3A: rs1550117 and DNMT3L: rs7354779)." (PMID 28894282, 2017). "Also, male infertility has been recently linked to a DNMT3B polymorphism in strong linkage with the -149C>T one, and several studies suggest association of MTHFR hyper-methylation with male infertility." (PMID 31370354, 2019). "We show that variants in the DNMT3B and DNMT1 may have different relationships with idiopathic male infertility." (PMID 28894282, 2017).
metastatic cancer (2 papers, 2010 to 2022). A carcinoma which has spread from the original site of growth to another anatomic site. "It was found that DNMT3B mediated epigenetic reprogramming in metastases, innovatively linking the metastatic microenvironment to epigenetic alterations occurring in metastases, which suggested that DNMT3B could be an underlying target for the treatment of metastatic cancer." (PMID 36091786, 2022). "For example, we observed significantly increased levels of miR-148b in SCLC compared to HBECs; miR-148b has been shown to target DNMT3B, with down-regulation of miR-148b observed in metastatic cancers." (PMID 20624269, 2010).
monoclonal gammopathy (2 papers, 2024 to 2025). A condition characterized by the abnormal presence of monoclonal immunoglobulins in the blood or urine. "Freshly purified bone marrow plasma cells (CD138+) from MM patients have lower miR29b and higher DNMT3B (mRNA and protein) than do cells from patients with monoclonal gammopathy of undetermined significance." (PMID 38654298, 2024). "Finally, we also evaluated DNMT3B mRNA levels in primary samples of monoclonal gammopathy of undetermined significance (MGUS; n = 1), smoldering myeloma (SMM; n = 1), ND (n = 3) and relapsed (n = 3) MM patients using qPCR." (PMID 40241199, 2025).
myeloid malignancies (2 papers, 2020 to 2021). "Thus, our data identify Dnmt3b as a haploinsufficient tumor suppressor gene in the prevention of TCLs and CLL that also may play a role in prevention of myeloid malignancies in mice." (PMID 33450231, 2021).
myeloproliferative disease (2 papers, 2021 to 2023). "Furthermore, HOXB3 whose overexpression is associated with myeloproliferative neoplasm (MPN) disorders recruits DNMT3B to bind in the pre-miR-375 promoter." (PMID 37345170, 2023).
Non-Alcoholic Steatohepatitis (2 papers, 2019 to 2023). "miR-29a can directly target the 3’-UTR of Dnmt3b to reduce DNA methylation modification in developing nonalcoholic steatohepatitis." (PMID 37298111, 2023).
oral lichen planus (2 papers, 2020 to 2021). Oral lichen planus is a chronic inflammatory oral condition of unknown aetiology characterized by T-cell-mediated chronic immune response and abnormal epithelial keratinization cycle. "For example, DNMT3A and DNMT3B are increased in lip and oral carcinogenesis, and high levels of DNMT1 can also be seen in oral lichen planus." (PMID 35048062, 2021).
oropharyngeal cancers (2 papers, 2019 to 2020). Carcinoma, predominantly squamous cell, arising from the epithelial cells of the oropharynx. "A similar differential analysis in the HPV- cohort indicated a panel completely distinct from the HPV+ oropharyngeal cancers; FADD (Fas Associated via Death Domain, 41%), FKBP9 (FKBP Prolyl Isomerase 9, 24%), FLNA (Filamin A, 24%) and DNMT3B (DNA Methyl transferase 3 Beta, 18%) with high prevalence." (PMID 31310629, 2019).
ovarian tumor (2 papers, 2012 to 2023). "In the present study, we for the first time immunohistochemically determined the expression of DNMT1, DNMT3a, and DNMT3b proteins in benign and malignant ovarian tumor tissues." (PMID 22768205, 2012).
Pseudomonas infection (2 papers, 2021 to 2022). Infections with bacteria of the genus pseudomonas. "To determine a role for flagellin in Dnmt3b-mediated inhibition of the immune response in bronchiolar epithelial cells and bacterial clearance during Pseudomonas infection in vivo, we infected Dnmt3bfl/flCc10Cre and control mice with PAKflic via the airways." (PMID 33793661, 2021). "Opposite to these results, we show here that the absence of Dnmt3b in macrophages does not impact on cytokine production during Pseudomonas infection in vivo." (PMID 35269409, 2022).
sarcoma (2 papers, 2022 to 2025). A usually aggressive malignant neoplasm of the soft tissue or bone. "In synovial sarcoma, the mRNA expression levels of DNMT1 and DNMT3B were similar to or lower than those in other sarcomas, whereas DNMT3A exhibited higher expression levels." (PMID 40299558, 2025).
Stroke (2 papers, 2018 to 2024). Sudden impairment of blood flow to a part of the brain due to occlusion or rupture of an artery to the brain. "The levels of DNMT3a, DNMT3b, and DNMT1 in the contralesional cortex after a stroke (p < 0.001, n = 6) significantly increased." (PMID 29997355, 2018). "Encouragingly, shRNAs against Dnmt3b, Pcgf6, and Mga were among those that are enriched after OGD treatment, consistent with the notion that DNA methylation and polycomb repressive complexes play important roles in stroke injury and neuroprotection." (PMID 38372724, 2024).
synovial sarcoma (2 papers, 2024 to 2025). "We first investigated whether the genes that regulate DNA methylation (DNMT1, DNMT3A, DNMT3B, TET1, TET2, TET3) are misexpressed, mutated, or amplified in synovial sarcoma." (PMID 40299558, 2025).
Tatton Brown Rahman syndrome (2 papers, 2021 to 2023). "Here, we focused on rare early onset developmental disorders with loss-of-function (LoF) pathogenic variations in DNMT3A (Tatton-Brown-Rahman syndrome; TBRS) and in DNMT3B (Immunodeficiency Centromeric instability and Facial dysmorphism; ICF)." (PMID 33916664, 2021).
testicular germ cell tumor (2 papers, 2019 to 2021). A germ cell tumor arising from the testis. "miR-1291 targets DNA methyltransferases (Dnmt3a, Dnmt3b) that are involved in (de novo) histone methylation, genomic imprinting, X-chromosome inactivation, and testicular germ cell tumors due to exposure to alkylphenols." (PMID 34199666, 2021).
type 2 diabetes (2 papers, 2013 to 2022). "For example, individuals with type 2 diabetes had higher DNMT3B levels in cultured myotubes and decreased TET1 expression in adipose tissue vs tissue from individuals without type 2 diabetes, while palmitate exposure decreased DNMT3A and DNMT1 expression in human pancreatic islets." (PMID 35307762, 2022).
varicocele (2 papers, 2021 to 2024). A condition characterized by the dilated tortuous veins of the spermatic cord with a marked left-sided predominance. "In a study by Rashidi and colleagues, the expression of DNMT3A and DNMT3B was elevated in 35 men with varicoceles at both the mRNA and protein levels." (PMID 38392299, 2024). "Incontrast to DNMT1, expression and percentage of DNMT3A and DNMT3B at RNA and protein levels were significantlyhigher in the varicocele group compared to the fertile group (P<0.05)." (PMID 34455713, 2021). "Our findings indicated that in contrast to the percentage of DNMT1 positive sperm, the mean percentagesof DNMT3A and DNMT3B positive sperm weresignificantly higher in varicocele group than fertilegroup." (PMID 34455713, 2021). "Hypo-methylation and high expressionof DNMT3A and DNMT3B at both mRNA and proteinlevels may be part of a compensative mechanism of thecell in varicocele state or play a dual role in oxidativestress condition." (PMID 34455713, 2021). "However,percentage of DNMT3A (fertile: 48.34 ± 6.35 vs.varicocele, 65.42 ± 3.9, P=0.02) and DNMT3B positivesperm (fertile: 64.31 ± 4.8 vs. varicocele: 76.61 ± 3.1,P=0.03) were significantly higher in varicocele comparedto fertile group." (PMID 34455713, 2021). "In addition, there was a positive significantcorrelation between sperm concentration with percentageof DNMT3B positive sperm in varicocele group." (PMID 34455713, 2021). "Negative correlationswere observed between percentage of sperm abnormalmorphology with percentage of DNMT1, DNMT3Aand DNMT3B positive sperm in varicocele group.Percentage of DNMT3A positive sperm also had negativesignificant correlation with percentage of sperm abnormalmorphology in fertile group." (PMID 34455713, 2021). "This might suggest thataltered DNA methylation in varicocele state is not dueto aberration of DNA maintenance, but it is rather dueto altered activity of DNMT3A and DNMT3B enzymesinvolved in de novo DNA methylation." (PMID 34455713, 2021).
acute kidney injury (1 paper, 2023). Sudden and sustained deterioration of the kidney function characterized by decreased glomerular filtration rate, increased serum creatinine or oliguria. "Although DNMT3A and DNMT3B knock-out mice displayed no obvious kidney abnormalities, they showed resistance to acute kidney injury (AKI)." (PMID 37928907, 2023).
acute leukemia (1 paper, 2019). A clonal (malignant) hematopoietic disorder with an acute onset, affecting the bone marrow and the peripheral blood. "In addition, HOTAIR has been revealed to be correlated to upregulated Dnmt3a and Dnmt3b via the regulation of the DNA methylation in acute leukemia patients, contributing to the induced occurrence of acute leukemia." (PMID 31168296, 2019).
agammaglobulinemia (1 paper, 2022). A decreased level of serum immunoglobulins. "More than 18% of all patients with syndromic CIDs, including most cases with DNMT3B/ZBTB24 mutations, were clinically diagnosed with antibody deficiencies before genetic evaluation." (PMID 36544766, 2022). "More than 18% of all patients with syndromic CIDs, including most DNMT3B/ZBTB24 mutations patients, were clinically diagnosed with antibody deficiencies before genetic evaluation." (PMID 36544766, 2022). "More than 18% of all patients with syndromic CIDs, especially most of our patients with DNMT3B/ZBTB24 mutations, were initially misdiagnosed as predominantly antibody deficiencies before genetic evaluation." (PMID 36544766, 2022). "Most patients in the ATM (92.5%) and STAT3 (AD-LOF) (89.5%) groups had similar clinical diagnoses, however, patients with DNMT3B/ZBTB24 mutations were first diagnosed with hypogammaglobulinemia (13, 68.4%), immunoglobulin A deficiency (2, 10.5%), and agammaglobulinemia (1, 5.3%)." (PMID 36544766, 2022). "It possibly stems from the shared immunologic features of hypogammaglobulinemia and normal B cell counts in the absence of remarkable facial abnormalities in our DNMT3B/ZBTB24-mutated patients." (PMID 36544766, 2022).
alcohol abuse (1 paper, 2019). The use of alcoholic beverages to excess, either on individual occasions ("binge drinking") or as a regular practice. "Expression of DNMT1, DNMT3B and DNMT3L was identified to be negatively correlated with the expression of TNFRSF12A in 116 HCC with alcohol abuse (r <−0.22, p < 0.01)." (PMID 31998364, 2019).
allergic rhinitis (1 paper, 2025). Inflammation of the nasal mucous membranes caused by an IgE-mediated response to external allergens. "This hypothesis is supported by previous research showing that SFRP5 expression is downregulated in allergic rhinitis, that may be attributed to DNMT3B-driven DNA methylation." (PMID 40595027, 2025).
Allergy (1 paper, 2022). An allergy is an immune response or reaction to substances that are usually not harmful. "The patients with ATM predominantly presented ataxia/telangiectasia (46.2%) and infections (32.1%), while allergy (52.6%) and infection (94.4%) were the dominant first manifestations in STAT3 (AD-LOF) and DNMT3B/ZBTB24 mutations, respectively." (PMID 36544766, 2022).
ameloblastic carcinoma (1 paper, 2021). A rare, cytologically malignant ameloblastoma that may metastasize. "Therefore, we aimed to investigate DNMT1, DNMT3A, DNMT3B, and H3K9ac immunohistochemical expression in the most prevalent and locally aggressive benign odontogenic tumor, ameloblastoma, and compare this with its malignant counterpart, ameloblastic carcinoma (AC)." (PMID 35048062, 2021). "This study aimed to describe the immunohistochemical expression of DNMT1, DNMT3A, DNMT3B, and H3K9ac in the dental follicle (DF), ameloblastoma (AME), and ameloblastic carcinoma (AC), correlating these expressions with the recurrence and aggressive behavior in ameloblastoma." (PMID 35048062, 2021).
ameloblastoma (1 paper, 2021). The most common odontogenic tumor, arising from the epithelial component of the embryonic tooth and usually affecting the molar-ramus region of the mandible or maxilla. "The ameloblastomas with BRAFv600e mutation, vestibular/lingual, or vestibular/palatine bone cortical disruption and maxilla involvement showed DNMT1 overexpression, while recurrent cases had high DNMT3B levels." (PMID 35048062, 2021).
amyotrophic lateral sclerosis (1 paper, 2023). Amyotrophic lateral sclerosis (ALS) is a neurodegenerative disease characterized by progressive muscular paralysis reflecting degeneration of motor neurons in the primary motor cortex, corticospinal tracts, brainstem and spinal cord. "Similarly, DNMT3B and SRCAP variants have also been linked to neurodegenerative disorders, including Alzheimer’s disease (AD), PD, and amyotrophic lateral sclerosis (ALS)." (PMID 36814905, 2023).
arteriosclerosis (1 paper, 2020). A vascular disorder characterized by thickening and hardening of the walls of the arteries. "First, we evaluated the expression levels of CREG and DNMT3B in atherosclerotic arteries from patients with arteriosclerosis obliterans who had undergone amputation and control arteries from amputees without arteriosclerosis." (PMID 32067910, 2020).
ATRX syndrome (1 paper, 2010). "Although ATRX does not contain a canonical DNA methyltransferase motif, DNMT3B and ATRX share a closely related plant homeodomain (PHD)-like zinc finger domain and patients with ATRX syndrome exhibit alterations in DNA methylation at repetitive sequences." (PMID 20885787, 2010).
Autoimmunity (1 paper, 2022). The occurrence of an immune reaction against the organism's own cells or tissues. "Altered phosphorylation of STAT3 in STAT3 deficiency or DNA methylation in DNMT3B and ZBTB24 are probably accounted for the autoimmunity in these diseases." (PMID 36544766, 2022). "A comprehensive comparison in terms of demographic, clinical, and immunological features was performed between patients with and without autoimmunity and also among four mutation groups with the most registered cases including ATM, STAT3 (AD-LOF), DNMT3B/ZBTB24, and WAS mutations." (PMID 36544766, 2022).
bacterial pneumonia (1 paper, 2021). Acute infection of the lung parenchyma caused by bacteria (e.g., Streptococcus pneumoniae, Haemophilus influenzae, Chlamydia pneumoniae, Mycoplasma pneumoniae, and Legionella pneumophila). "To further examine the role of flagellin in Dnmt3b regulated functions during bacterial pneumonia we infected Dnmt3bfl/flCc10Cre and control mice with Klebsiella pneumoniae, an un-flagellated gram-negative bacterium." (PMID 33793661, 2021).
bile duct cancer (1 paper, 2022). "The methylation profile of the CDKN2B promoter, a cell cycle inhibitor gene, was reduced in cells overexpressing miR‐29b that inhibits bile duct cancer progression by releasing DNMT3B‐mediated inhibition of CDKN2B expression." (PMID 34970791, 2022).
brain tumors (1 paper, 2021). "In embryonal brain tumors associated with C19MC, this fusion dysregulated and increased expression of a DNMT3B isoform—a DNA methyltransferase that is found specifically in embryonic brains and is associated with significant overexpression in pediatric brain tumors." (PMID 34262434, 2021).
cholestasis (1 paper, 2017). Impairment of the bile flow caused by obstruction within the liver, or outside the liver in the bile duct system. "In the BDL-miR-29aTg group, the abundances of DNMT1, DNMT3b and SET1A were significantly lower than those in the BDL-WT group (p < 0.001, respectively), which was suggestive of the active responses of these molecules to miR-29a signaling in early cholestasis." (PMID 28106784, 2017).
chronic asthma (1 paper, 2021). An asthma that is characterized by the development of persistent airway inflammation and recurrent attacks of breathlessness and wheezing, which vary in severity and frequency. "Immunohistochemical analysis confirmed that de novo methyltransferase DNMT3a and DNMT3b were significantly decreased in chronic asthma compared with the control group, and was especially expressed in bronchial epithelium." (PMID 35058921, 2021). "We measured the expression of DNA methyltransferase and found that the expression of DNMT3a and DNMT3b were significantly decreased in chronic asthma while DNMT1 did not have any statistical difference." (PMID 35058921, 2021).
colonic adenomas (1 paper, 2013). "In fact, de-novo methylation might be harmful in this system, as overexpression of DNMT3b is associated with increased formation of colonic adenomas, while Dnmt3b deletion prevents neoplasia formation." (PMID 23714178, 2013).
congenital heart disease (1 paper, 2022). A heart disease that is present at birth. "One recent study suggests DNMT3B protein increases in lungs of congenital heart disease–associated PH patients and rats exposed to monocrotaline or Hx, and knockdown of Dnmt3b in rats exacerbates monocrotaline- and Hx-induced PH." (PMID 36372233, 2022).
Crohn ́s disease (1 paper, 2022). "We found that DNMT3A mRNA levels, but not DNMT3B nor DNMT1, were significantly reduced in both inflamed and non inflamed samples from Crohn ́s disease (CD), but also from ulcerative colitis patients, compared to healthy individuals." (PMID 36271073, 2022).
cryptorchidism (1 paper, 2020). The failure of one or both testes of a male fetus to descend from the abdomen into the scrotum during the late part of pregnancy. "Sperm deformities and cryptorchidism were observed, which was associated with raised Dnmt levels (Dnmt1, Dnmt3a, Dnmt3b)." (PMID 32398147, 2020).
cystic fibrosis (1 paper, 2012). Autosomal recessive disorder caused by pathogenic variants in the CFTR gene (cystic fibrosis transmembrane conductance regulator), which encodes a chloride and bicarbonate channel expressed in epithelial cells, and follow the diagnosis criteria. "In CFPAC-1 cells, derived from a pancreatic ductal adenocarcinoma liver metastasis of a patient with cystic fibrosis, a borderline significant rhythmicity with a 24 h period was found for the PPARG, DNMT1, and DNMT3B expression patterns, and the time-qualified profiles showed different shapes." (PMID 22966223, 2012).
depression (1 paper, 2020). "In another study, the DNMT3B expressions in the dorsolateral prefrontal cortex of depression patients were increased, and the DNMT3A expressions showed no change compared to those in healthy controls." (PMID 33101076, 2020). "In summary, given the contradictory observations among the studies of DNMT3A and DNMT3B in depression patients and depression-like animal models, it is still early to draw a conclusion based on the available data." (PMID 33101076, 2020). "However, one study suggests DNMT3B may also change in depression, paralleling DNMT3A." (PMID 33101076, 2020).